TLR1 (toll like receptor 1)
Diseases named in the same sentence as TLR1 in open-access papers (continued):
Sharing a sentence is not in itself a finding about the gene and the disease.
gastric cancer (5 papers, 2015 to 2025). A primary or metastatic malignant neoplasm involving the stomach. "We re-investigated this association in an updated genome-wide association study (GWAS) meta-analysis for populations with low gastric cancer incidence, address potential causes of cohort heterogeneity, and explore functional implications of genetic variation at the TLR1/6/10 locus." (PMID 35031300, 2022). "A recent study proved that TLR1 rs4833095 and TLR10 rs10004195 gene polymorphisms are associated with a higher risk of gastric cancer in H. pylori-infected individuals." (PMID 30863783, 2019). "TLR1 and TLR10 gene polymorphisms were associated with a higher risk for gastric cancer in H. pylori-infected individuals." (PMID 30863783, 2019). "However, in another study, the expression of TLR1, TLR2, TLR4, TLR5 and TLR6 was associated with survival in gastric cancer, and only high cytoplasmic TLR2 expression was shown to be significantly associated with a poorer 5-year survival." (PMID 40362298, 2025). "Therefore, in this study, we aimed to explore the tissue expression of TLR1, TLR2, TLR4, TLR5, TLR7, and TLR9 as potential prognostic biomarkers in gastric cancer patients, and to examine their associations with several clinicopathological variables." (PMID 31467388, 2019). "In addition, we found that a high expression of TLR1, TLR2, TLR4, TLR5, TLR7, and TLR9 associated with an intestinal-type gastric cancer and with a high expression of all other TLRs." (PMID 31467388, 2019). "Recently, the tissue expressions of TLR1, TLR2, TLR4, TLR5, TLR7 and TLR9 as potential prognostic biomarkers in gastric cancer were reported, showing a positive correlation between each other and a high expression of each studied TLR in tumors with an intestinal-type histology." (PMID 40362298, 2025). "Thus, we aimed to evaluate the tissue expressions of TLR1, TLR2, TLR4, TLR5, TLR7, and TLR9 as potential prognostic biomarkers in gastric cancer." (PMID 31467388, 2019). "In addition to TLR5, TLR1, TLR2, TLR4, TLR7, and TLR9 were also expressed in gastric cancer tissues, yet their expression levels did not function as prognostic biomarkers across the entire patient cohort." (PMID 31467388, 2019).
influenza (5 papers, 2013 to 2025). An acute viral infection of the respiratory tract, occurring in isolated cases, in epidemics, or in pandemics; it is caused by serologically different strains of viruses (influenzaviruses) designated A, B, and C, has a 3-day incubation period, and usually lasts for 3 to 10 days. "In ageing, defects in TLR1/2 expression and signaling are potentially associated with higher risk of infection and poor vaccine responses, e.g. to influenza." (PMID 23391127, 2013). "Additionally, using poly I:C (TLR3) and Pam3CSK4 (TLR1/2) adjuvant combination for influenza and anthrax vaccine enhanced antibody production by B-cell in vivo." (PMID 40277916, 2025).
leukemia (5 papers, 2011 to 2022). A malignant (clonal) hematologic disorder, involving hematopoietic stem cells and characterized by the presence of primitive or atypical myeloid or lymphoid cells in the bone marrow and the blood. "Further studies are necessary to elucidate the role of the TLR1, TLR4, TLR5, TLR6, TLR9, and CD14 polymorphisms in the pathogenesis of leukemia." (PMID 36071076, 2022). "In this study, the NK cells from peripheral blood of patients with leukemia show a significant decrease in the expression of TLR1, but not of TLR2." (PMID 34567117, 2021).
mastitis (5 papers, 2009 to 2025). Inflammation of breast tissue during lactation or postpartum due to an obstructed duct or infection. "Single nucleotide polymorphisms in the PRRs TLR-1 and 2 have been associated with increased risk of mastitis in cattle, and it is expected that SNPs in TLRs affect the recognition of pathogens." (PMID 31842337, 2019). "The objective of this study was to investigate whether single nucleotide polymorphisms (SNPs) within the bovine TLR1 gene (boTLR1) are associated with clinical mastitis (CM)." (PMID 22417166, 2012).
myeloma (5 papers, 2013 to 2025). "This study explored the effect of TLR1/2 ligand (Pam3CSK4) alone or combined with bortezomib (BTZ) on production of FLCs in human myeloma cell lines, L363, OPM-2, U266 and NCI-H929." (PMID 39874349, 2025). "OPM-1, OPM-2 and NCI-H929 myeloma cell lines showed a decrease in adhesion to BMSCs after TLR-1/2 activation, which was accompanied with a down-regulation in surface expression of β7 integrin." (PMID 24794258, 2014). "In a recent study, we demonstrated that TLR1/2 activation either increased or decreased adhesion of human myeloma cells to fibronectin and modulated cytotoxicity of bortezomib in HMCLs." (PMID 24794258, 2014). "In the present study, we explored the modulatory effects of TLR1/2 ligand (Pam3CSK4) on adhesion of human myeloma cells to BMSCs." (PMID 24794258, 2014). "Stimulation of TLR1/2 bypasses the protective shield of BMSCs and may be an interesting strategy to enhance drug sensitivity of multiple myeloma cells." (PMID 24794258, 2014). "Analysis of toll-like receptor (TLR) expression at protein level indicated that TLR1, TLR3, TLR4, TLR7, TLR8, and TLR9, were similarly expressed in most human myeloma cell lines, including L363 and RPMI 8226 cells, as well as in primary cells from MM patients." (PMID 28702457, 2017). "Expression of mRNA for TLR1, TLR3, TLR4, TLR5, TLR7, TLR8, and TLR9 was found in all myeloma cell, but levels of mRNA expression differed amongst different cell lines." (PMID 23593278, 2013). "Importantly, TLR1/2 triggering increased cytotoxic and apoptotic effects of bortezomib in myeloma cells independent of the effect on stromal cell adhesion." (PMID 24794258, 2014).
prostate carcinoma (5 papers, 2009 to 2024). A carcinoma that arises from epithelial cells of the prostate gland. "Lastly, Black men with prostate cancer, which we found are more sensitive to TLR1/2 stimulation, have higher inflammatory signatures—including that of type I IFNs— in their tumors." (PMID 39320053, 2024). "We showed that prostate cancer cell lines differentially express TLR1-10, MyD88 and CD14 transcripts." (PMID 24966802, 2014). "Within those sub-pathways, 5 genes (TLR1, TLR6, OAS1, OAS2, and COX-2) were nominally associated with advanced prostate cancer risk." (PMID 23272139, 2012). "Ligands of TLR1/2 have been identified in tumors, and bacteria have been reported to colonize diverse tumor types, including prostate cancer, which may trigger TLR1/2 signaling." (PMID 39320053, 2024). "Two sub-pathways (intracellular antiviral molecules and extracellular pattern recognition) and four genes in these sub-pathways (TLR1, TLR6, OAS1, and OAS2) were nominally associated with advanced prostate cancer risk and harbor several SNPs nominally associated with advanced prostate cancer risk." (PMID 23272139, 2012). "Expression of TLR1-10, MyD88 and CD14 in prostate cancer cells, LNCaP, PC3 and DU145, was studied by RT-PCR." (PMID 24966802, 2014). "Therefore we examined and compared expression of TLR1-10, MyD88 and CD14 and functional responsiveness to TLR-2 and 4 ligands in well-established prostate cancer cell lines." (PMID 24966802, 2014).
acute lymphoblastic leukemia (4 papers, 2014 to 2022). Leukemia with an acute onset, characterized by the presence of lymphoblasts in the bone marrow and the peripheral blood. "Our study demonstrated that TLR6 C > T rs5743810 and TLR9 C > T rs5743836 polymorphisms are associated with the risk of acute lymphoblastic leukemia and TLR1 T > G rs5743618 and TLR9 C > T rs5743810 is involved with death." (PMID 36071076, 2022). "In acute lymphoblastic leukemia (ALL) cell lines, TLR1, TLR2, TLR3, TLR4, TLR6 and TLR7 are expressed albeit at variable levels." (PMID 25112836, 2014). "For example, Rolf and colleagues demonstrated that stimulation of acute lymphoblastic leukemia (ALL) cell lines and primary ALL samples with the specific TLR1/2 agonist, PAM3CSK4, versus the TLR2/6 agonist, PAM2CSK4, led to distinct activation kinetics of the NF-κB and PI3K pathways." (PMID 27733853, 2016).
bronchiolitis (4 papers, 2016 to 2025). Inflammation of the bronchioles characterized by swelling of the bronchioles and mucus accumulation. "Toll-like receptor 1, 2, 3, 4, 6, 7, 8, 9 and 10 genotype and minor allele frequencies in 98 children hospitalised for bronchiolitis and the Finnish population." (PMID 26741133, 2016). "The joint analyses of the TLR1 rs5743618, TLR2 rs5743708, TLR6 rs5743810 and TLR10 rs4129009 genotype combinations and baseline (z-scores) and hyper-reactivity IOS measurements (Δz-scores) in 97 children hospitalized for bronchiolitis." (PMID 26741133, 2016).
eczema (4 papers, 2022 to 2024). "Both TLR1 and TLR10 have also been associated with AD and eczema in human GWAS79,80." (PMID 36482174, 2022).
fungal infections (4 papers, 2014 to 2025). "It has been reported that a number of major SNPs are associated with susceptibility of fungal infections and diseases, including MBL2, TLR1/4/6/9, CARD9, CXCL2, DECTIN1, IL4/10/15/2, and HLA." (PMID 33362211, 2020). "Additionally, CD14, TLR1, and TLR2 have been investigated in fungal infection models before." (PMID 40098951, 2025).
glioma (4 papers, 2015 to 2022). A benign or malignant brain and spinal cord tumor that arises from glial cells (astrocytes, oligodendrocytes, ependymal cells). "Several genes linked to glioma pathogenesis have been discovered, but the prognostic and clinical importance of the TLR1 gene in glioma remains uncertain." (PMID 34869584, 2021). "Up to date, TLR2, TLR3, TLR4, TLR7, and TLR9 have been intensely studied in glioma, while less or missing information is available regarding the mechanisms of TLR1/TLR6 (dimerizes with TLR2), TLR5, TLR8 (dimerizes with TLR7), and particularly TLR10." (PMID 34715891, 2021). "We found the difference gene TLR1 between baseline group and post training group in the data set, and TLR1 was differentially expressed in low-grade glioma and normal population in TCGA data set." (PMID 34869584, 2021). "In glioma, elevated TLR1, TLR2, TLR4, TLR5, TLR6, and TLR9 expressions were observed in tumor cell lines and tissues compared with non-neoplastic brain tissues, particularly in the mesenchymal subtype of GBM." (PMID 34715891, 2021). "The expression of TLR1 and 4 was similar in glioma-derived CD11b+ cells and the TRL7 mRNA was up-regulated in GBM (not shown), therefore there was no defect in upstream TLR signaling." (PMID 26427514, 2015). "Finally, while enrichment analysis enabled us to investigate the biological process of TLR1 in gliomas, the comprehensive mechanism of linking TLR1 expression and TLR1 methylation with LGG development needs additional biomedical research." (PMID 34869584, 2021). "In addition, we verified the role of TLR1 in Glioma cell lines." (PMID 34869584, 2021). "The subsequent correlation analyses also indicated MD2 was strongly correlated with CD14, LY86, TLR1 and TLR4 in gliomas." (PMID 35372062, 2022).
cervical cancer (3 papers, 2017 to 2024). A primary or metastatic malignant neoplasm involving the cervix. "De Carlo reported a similar decrease in TLR1 gene expression in HPV+ cervical cancers." (PMID 29416610, 2018). "Thus, although TLR4 is considered an important marker of HPV+ cervical cancer, alterations in the levels of TLR1, TLR3 and TLR6 observed in HPV+ samples may be the target of investigations related to the tumor inflammatory process." (PMID 39208235, 2024). "When evaluating the gene expression patterns of TLR transcripts, specifically TLR1, TLR3, TLR4, TLR6, TLR7, TLR8 and TLR10, in HPV+ and HPV- cervical cancer tissue samples, we observed an increase in TLR4 expression and a decrease in TLR1 and TLR3 expression." (PMID 39208235, 2024). "According to a previous study, a reduction in TLR1 expression was detected in the malignant epithelium, and an increase in TLR3 expression was detected in the premalignant epithelium of the HPV+ cervical cancer tumor microenvironment." (PMID 39208235, 2024). "In our study, the reduction in TLR1 expression in the samples (HPV+ and HPV-) indicates a possible relationship with the stage of tumor development rather than with specificity to the type of cervical cancer." (PMID 39208235, 2024).
diabetes (3 papers, 2017 to 2025). "In the PCC group, there was a correlation between duration of diabetes and neutrophil TLR1 (r = −0.730, p = 0.04), TLR3 (r = 0.766, p = 0.03) and TLR5 (r = 0.843, p = 0.01) mRNAs." (PMID 28794498, 2017). "Further, after adjustment for age, sex, WHR, BMI, duration of diabetes, creatinine and medications using lognormal data with multifactorial ANOVA, TLR1, 3, 5, 6, 7, 9 and 10 mRNA levels remained statistically significant among the groups." (PMID 28794498, 2017).
endometriosis (3 papers, 2020). The growth of functional endometrial tissue in anatomic sites outside the uterine body. "Studies on TLRs in patients with endometriosis are very limited, with just a few data on the presence of TLR1, 2, 3, 4, 5, and 6 in the epithelia of different regions of the female reproductive tract." (PMID 32751735, 2020). "Accordingly, infertile women with endometriosis have a significantly higher expression of TLR1, 5, 6, 7, 8, 10 and significantly lower expression of TLR3, 9 when compared with normal women." (PMID 33209739, 2020). "TLR1, 5, 6, 7, 8 and TLR10 showed a significantly higher expression in endometriosis patients compared to the control (p<0.05)." (PMID 33209739, 2020).
IgA nephropathy (3 papers, 2014 to 2018). "Another well-characterized missense variant within the TLR1 gene, rs4833095, has been shown to be statistically associated with altered risk for IgA nephropathy in children, mortality in gram-positive sepsis and prostate cancer development." (PMID 29416723, 2018). "Previous studies indicated that TLR1 single nucleotide polymorphisms (SNPs) might be associated with the risk of IgA nephropathy (IgAN)." (PMID 27806314, 2016). "TLR1 and TLR9 expression levels are increased in apoferritin-induced nephritis, and TLR9 polymorphisms are related to many human diseases, including IgA nephropathy." (PMID 24810370, 2014).
pancolitis (3 papers, 2011 to 2018). Ulcerative colitis that involves the entire colon. "Polymorphisms in TLR1 and TLR2 genes (TLR1 R80T and TLR2 R753G) have been associated with pancolitis in UC patients." (PMID 21647408, 2011).
pancreatic cancer (3 papers, 2019 to 2021). "Here, we demonstrated that low TLR1 and ADA2 expression play vital roles in pancreatic cancer immunity and can both mediate immune cell infiltration to affect tumor immune status." (PMID 34654352, 2021). "Prognostic signature containing four IRGs (ADA2, TLR1, PTPN6, S100P) was constructed with good predictive performance; in particular, S100P played a significant role in the immune microenvironment, and tumorigenesis of pancreatic cancer." (PMID 34654352, 2021). "In the report of the TLR1 gene, elevated expression of TLR1 is corrected with a good prognosis of pancreatic cancer, but it has never been studied in LGG." (PMID 34869584, 2021). "Although the immune mechanisms of ADA2 and TLR1 have been studied in some tumors, they have not yet been studied in pancreatic cancer." (PMID 34654352, 2021). "In this study, we constructed an immune-related prognostic signature based on four immune-related genes (ADA2, TLR1, PTPN6, and S100P) that displayed good predictive ability for overall survival and analyzed the infiltration of corresponding immune cells in patients with pancreatic cancer." (PMID 34654352, 2021).
periodontitis (3 papers, 2019 to 2025). An acute or chronic inflammatory process that affects the tissues that surround and support the teeth. "Comparison of healthy and periodontitis tissues showed that periodontitis was characterized by loss of TLR1, TLR2, and TLR5 expression in the superficial epithelial cell layers." (PMID 31448244, 2019). "In a study on HIV-positive North American patients with periodontitis, 8 SNPs in 6 TLR genes (TLR1 (n = 2), TLR2 (n = 1), TLR4 (n = 1), TLR6 (n = 1), TLR8 (n = 2), and TLR9 (n = 1)) were positively associated with P. gingivalis (2 SNPs), T. denticola (6 SNPs), and T. forsythia (1 SNP)." (PMID 35122548, 2022).
psoriasis (3 papers, 2021 to 2024). An autoimmune condition characterized by red, well-delineated plaques with silvery scales that are usually on the extensor surfaces and scalp. "The percentage of inflammatory cells expressing TLR1 was greater than that of the psoriasis group (p = 0.021)." (PMID 35715478, 2022). "In general, TLR1 and TLR2 were expressed in the upper and middle epidermis of psoriasis lesions." (PMID 34790055, 2021). "In conclusion, elevated expression levels of TLR1, TLR2, TLR4, TLR7, and TLR9 may facilitate the occurrence of psoriasis." (PMID 34790055, 2021). "A study conducted on eight samples of normal skin and 15 samples of lesional and non-lesional biopsies from patients with psoriasis demonstrated that TLR1, TLR2, and TLR5 are constitutively expressed in the keratinocytes of normal skin." (PMID 34790055, 2021).
abscess (2 papers, 2020 to 2021). An inflammatory process characterized by the accumulation of pus within a newly formed tissue cavity which is the result of a bacterial, fungal, or parasitic infection or the presence of a foreign body. "In conclusion, this study showed that polymorphism TLR6 P249S plays a protective role, in contrast to polymorphism TLR1 R80T, in the severity of major abscesses, defined as lesion size at clinical presentation." (PMID 31786695, 2020). "Patients hetero- or homozygous for the allelic variant TLR6 P249S had smaller abscess lesions at clinical presentation and patients homozygous for the allelic variant TLR1 R80T had larger abscess lesions." (PMID 31786695, 2020). "Polymorphisms in TLR1 and TLR6 influence the severity of cSSSIs as assessed by the lesion size of major abscesses and DFIs." (PMID 31786695, 2020). "In patients with large abscesses, hetero- or homozygosity for the allelic variant TLR6 (P249S) was associated with significantly smaller lesions while homozygosity for the allelic variant TLR1 (R80T) was associated with significantly larger lesions." (PMID 31786695, 2020).
acne (2 papers, 2018 to 2024). An inflammatory process of the sebaceous glands which is characterized by comedones, nodules, papules and/or pustules on the skin. "In keratinocytes during acne vulgaris, Christie–Atkins–Munch-Petersen 1 factor (CAMP1) binds TLR2, and di- and tri-acylated lipoproteins engage TLR1/2 and TLR2/6 heterodimers, respectively." (PMID 39272974, 2024). "The available microarrays from whole tissue biopsies of acne samples (GSE53795), histological analysis and in vitro experiments all suggested a role for the TLR1/2 and TLR4 pathways in the pathogenesis of acne." (PMID 29927962, 2018). "Using a Venn diagram to visualize the up-regulated genes in the acne samples compared to healthy ones and in the TLR1/2- and TLR4-stimulated SZ95 sebocytes at 24 hours, a possible contribution of sebocytes with 92 of the 900 significantly altered transcripts in acne could be detected." (PMID 29927962, 2018).